NFIX (nuclear factor I X)
Diseases named in the same sentence as NFIX in open-access papers (continued):
Sharing a sentence is not in itself a finding about the gene and the disease.
head and neck squamous cell carcinoma (2 papers, 2020 to 2023). A squamous cell carcinoma that arises from any of the following anatomic sites: lip and oral cavity, nasal cavity, paranasal sinuses, pharynx, larynx, and salivary glands. "The results showed all the NFI family members were associated with OS in head and neck squamous cell carcinoma except NFIX." (PMID 32219034, 2020).
hepatocellular carcinoma (2 papers, 2024 to 2025). A malignant tumor that arises from hepatocytes. "In hepatocellular carcinoma, circRNA NFIX had been reported to be a key regulatory factor and a potential target for hepatocellular carcinoma." (PMID 39135128, 2024).
leukaemias (2 papers, 2020 to 2024). "This analysis also pointed to the higher expression of several other genes normally deregulated in a wide spectrum of leukaemias, including genes that act as transcriptional regulators (PRDM16 and NFIX) and a gene that influences proliferative advantage and survival (IGFBP2)." (PMID 32103106, 2020).
medulloblastoma (2 papers, 2021 to 2025). A malignant, invasive embryonal neoplasm arising from the cerebellum. "Moreover, ATAC-seq data suggest similar roles for NFIA and NFIB in the SHH subgroup of medulloblastoma, NFIB, and NFIX in prostate cancer, respectively." (PMID 39617063, 2025).
melanoma (2 papers, 2017 to 2020). A malignant, usually aggressive tumor composed of atypical, neoplastic melanocytes. "A2058 human melanoma cells engineered to over-express either BRN2 or MITF were analyzed by qRT-PCR for expression of all four members of the NFI gene family, NFIA, NFIB, NFIC and NFIX." (PMID 28119061, 2017).
muscular dystrophies (2 papers, 2023 to 2024). "The deleterious role played by NFIX in the context of muscular dystrophies has been associated with consecutive cycles of regeneration and degeneration." (PMID 36901722, 2023). "Furthermore, NFIX, elevated in myeloid subcluster 4 (tissue resident/epithelial‐like macrophages), can drive fibrosis in macrophages in murine models of muscular dystrophy." (PMID 38426634, 2024). "NFIX is normally not expressed in adult muscle stem cells (satellite cells), but its abnormal activation is associated with disease progression, namely in the context of muscular dystrophies." (PMID 36901722, 2023).
pituitary adenoma (2 papers, 2022 to 2024). "Procession of pituitary adenoma was enhanced by circRNA NFIX via CCNB1." (PMID 39135128, 2024). "Circ-NFIX was significantly expressed in invasive pituitary adenomas." (PMID 35883576, 2022). "Circ-NFIX regulated the expression of miR-34a-5p and CCNB1 during the in vivo and in vitro development and progression of pituitary adenomas." (PMID 35883576, 2022).
prostate carcinoma (2 papers, 2020 to 2025). A carcinoma that arises from epithelial cells of the prostate gland. "NFIX expression was lower in prostate carcinoma in Varambally’s study, but higher in benign prostate hyperplasia according to Tomlins’s dataset." (PMID 32219034, 2020). "Although NFIX expression was not downregulated in kidney, colorectal and prostate cancers." (PMID 32219034, 2020).
acute myeloid leukemia (1 paper, 2024). Acute myeloid leukemia (AML) is a group of neoplasms arising from precursor cells committed to the myeloid cell-line differentiation. "Process of acute myeloid leukemia was suppressed by circRNA NFIX interference." (PMID 39135128, 2024).
alcoholic cirrhosis (1 paper, 2024). "Hypermethylated DMRs observed in alcoholic cirrhosis and alcoholic HCC were found in forkhead box K1 (FOXK1), zinc finger CCCH-type containing 3 (ZC3H3), nuclear factor IX (NFIX), histone deacetylase 4 (HDAC4), and tetraspanin 9 (TSPAN9) genes." (PMID 38302914, 2024).
anal carcinoma (1 paper, 2024). "Finally, NFIX was the preferential target for HPV16 in anal carcinoma (5/7)." (PMID 38672666, 2024).
autistic spectrum disorder (1 paper, 2025). "Case 1035: Splicing outlier analysis identified increased usage of exon 9 of the NFIX gene (NM_002501) in the blood sample obtained from a male with constitutional overgrowth, autistic spectrum disorder, pectus excavatum, and advanced bone age." (PMID 40593860, 2025).
bladder cancer (1 paper, 2020). "High expression of NFIA, NFIC and NFIX predicted worse survival outcome in patients with bladder cancer." (PMID 32219034, 2020). "Reduced mRNA expression of NFIA, NFIB and NFIX predicted better OS in bladder cancer." (PMID 32219034, 2020).
callosal agenesis (1 paper, 2023). "Interestingly, haploinsufficiency of the NFIB and NFIX genes also causes callosal agenesis, and missense mutations in the NFIX gene have been associated with Sotos-like features." (PMID 37915986, 2023).
cholangiocarcinoma (1 paper, 2023). A carcinoma that arises from the intrahepatic biliary tree (intrahepatic cholangiocarcinoma) or from the junction, or adjacent to the junction, of the right and left hepatic ducts (hilar cholangiocarcinoma). "However, NFIX was upregulated in cholangiocarcinoma (CHOL), kidney renal clear cell carcinoma (KIRC), and liver hepatocellular carcinoma (LIHC)." (PMID 37686043, 2023).
chordoma (1 paper, 2023). Chordomas are rare malignant tumors arising from embryonic remnants of the notochord in axial skeleton. "Chordoma-specific DMRs were also found in location of homeobox domain genes (e.g. DMRs in HOXA4, HOXA5, HOXD3, HOXD4 MNX1, and NFIX) especially on chromosome 2 at HOXD cluster." (PMID 37434245, 2023).
Dravet syndrome (1 paper, 2024). "However, the mechanisms by which the Angelman and Dravet syndromes ASOs operate to increase productive RNA transcripts, and consequently protein expression, are not applicable to this case due to the nature of the patient’s NFIX mutation." (PMID 39518712, 2024).
ductal breast carcinoma (1 paper, 2020). "NFIX mRNA level was also significantly downregulated in ductal breast carcinoma compared with normal tissues in Sorlie, Perou and Sorlie2 databases." (PMID 32219034, 2020).
esophageal adenocarcinoma (1 paper, 2020). A malignant tumor with glandular differentiation arising predominantly from Barrett mucosa in the lower third of the esophagus. "Low expression of NFIC and NFIX revealed poor prognosis in esophageal adenocarcinoma patients." (PMID 32219034, 2020).
hemoglobinopathies (1 paper, 2023). "Identification and validation of NFIX as a new target for HbF activation has implications in the development of therapeutics for hemoglobinopathies." (PMID 37316562, 2023). "The robustness of the HbF phenotype upon NFIX knockdown and the potential tractability of targeting NFIX by genetic engineering approaches make it an important new target that could yield a therapeutic benefit to hemoglobinopathy patients." (PMID 37316562, 2023).
Infertility (1 paper, 2025). "Some infertility-related genes were identified in these networks, including DAZ family genes (DAZ1, DAZ3, and DAZ4), NF1 family TF motifs (NFIX), and ras association domain family 8 (RASSF8)." (PMID 40391511, 2025).
kidney chromophobe cell carcinoma (1 paper, 2020). "Regarding kidney chromophobe cell carcinoma, regression analysis confirmed a moderately negative correlation in NFIA (Pearson’s r = −0.4), NFIC (Pearson’s r = −0.4) and NFIX (Pearson’s r = −0.42)." (PMID 32219034, 2020). "Contrary to kidney chromophobe cell carcinoma, expression of NFIA and NFIB was upregulated in kidney papillary cell carcinoma and expression of NFIC and NFIX was reduced." (PMID 32219034, 2020). "In addition, expression of NFIA and NFIB was downregulated in kidney chromophobe cell carcinoma, whereas expression of NFIC and NFIX was upregulated." (PMID 32219034, 2020).
kidney clear cell carcinoma (1 paper, 2020). "Consistent with the trend observed in the Oncomine database, NFIA, NFIB and NFIX were significantly overexpressed in kidney clear cell carcinoma compared with normal kidney tissue." (PMID 32219034, 2020).
large cell lung carcinoma (1 paper, 2020). "NFIX expression was also lower in large cell lung carcinoma according to Garber’s database." (PMID 32219034, 2020).
liver cancer (1 paper, 2020). An epithelial or non-epithelial malignant neoplasm that arises from the liver. "In the KM plotter database, high NFIA and NFIX expression predicted better OS and disease-specific survival (DSS) in liver cancer patients." (PMID 32219034, 2020).
myocardial infarction (1 paper, 2024). Gross necrosis of the myocardium, as a result of interruption of the blood supply to the area, as in coronary thrombosis. "Knockdown of circ-Nfix (Nuclear Factor I X) in mice enhanced cell proliferation and angiogenesis and suppressed apoptosis, thereby promoting cardiac regenerative repair post-myocardial infarction." (PMID 39272989, 2024).
nasopharyngeal carcinoma (1 paper, 2020). A carcinoma arising from the nasopharyngeal epithelium. "NFIA and NFIX were reduced in tonsillar carcinoma, nasopharyngeal carcinoma, and oral cavity squamous cell carcinoma, respectively." (PMID 32219034, 2020).
periodontitis (1 paper, 2024). An acute or chronic inflammatory process that affects the tissues that surround and support the teeth. "The integration of GWAS with the expression quantitative trait locis of these genes from the peripheral blood genetically prioritized 6 candidate genes, including 2 risk genes (RAP2A, MCUR1) and 4 protective genes (WNK1, NFIX, FOS, PANX1) in periodontitis-related T2D." (PMID 38811930, 2024). "The integration of GWAS with the eQTLs of these genes from the peripheral blood prioritized 6 genes, including MCUR1, RAP2A, FOS, PANX1, NFIX and WNK1, in the pathogenesis of periodontitis-related T2D." (PMID 38811930, 2024). "MCUR1, RAP2A, FOS, PANX1, NFIX and WNK1 may play important roles in the pathogenesis of periodontitis-related T2D, shedding light on the development of potential drug targets." (PMID 38811930, 2024). "Furthermore, MCUR1, RAP2A, FOS, PANX1, NFIX and WNK1 were verified to play important roles in the pathogenesis of periodontitis-related T2D, shedding light on the discovery of potential drug targets for periodontitis patients to prevent T2D." (PMID 38811930, 2024).
small cell lung carcinoma (1 paper, 2025). Small cell lung cancer (SCLC) is a highly aggressive malignant neoplasm, accounting for 10-15% of lung cancer cases, characterized byrapid growth, and early metastasis. "Some examples are NFIB and NFIX’s role in super-enhancer maintenance of hair follicle stem cells, NFIB’s prometastatic actions in small cell lung cancer, and the recent identification of NFIB as a genome organizer in the prereplication complex." (PMID 39617063, 2025).
solitary fibrous tumor (1 paper, 2021). Solitary fibrous tumor (SFT) represents a diverse group of ubiquitous rare spindle cell neoplasms that may be benign or malignant and that most frequently arises from the pleura and peritoneum and rarely from other sites such as head and neck, liver and skeletal muscle. "In the present study, a new gene fusion consisting of Nuclear Factor I X (NFIX), mapping to 19p13.2 and STAT6, mapping to 12q13.3 was identified by targeted RNA-Seq in a 74-year-old female patient diagnosed with a deep-seated solitary fibrous tumor in the pelvis." (PMID 34299133, 2021).
squamous cell lung carcinoma (1 paper, 2020). A carcinoma arising from squamous bronchial epithelial cells. "No gene showed statistical significance for squamous cell lung carcinoma patients except NFIX, which was associated with OS." (PMID 32219034, 2020).
syringomyelia (1 paper, 2022). Syringomyelia is characterized by cerebrospinal fluid (CSF)-filled cavities (syrinx) inside the spinal cord, either as a result of a known cause (secondary syringomyelia, SS) or, more rarely, due to an unknown cause (primary syringomyelia, PS). "Three out seven patients had a co-occurring CACNA1A deletion, one subject had a microdeletion not involving CACNA1A but was affected with CM1 and syringomyelia and one subject (Pt 1) carrying a pathogenetic NFIX variant had CM1 with syringomyelia." (PMID 35717370, 2022).
tongue squamous cell carcinoma (1 paper, 2020). A squamous cell carcinoma that arises from the tongue. "In addition, expression of NFIB and NFIX was downregulated in tongue squamous cell carcinoma according to Estilo’s study." (PMID 32219034, 2020).
cancer (26 papers, 2016 to 2025). A tumor composed of atypical neoplastic, often pleomorphic cells that invade other tissues. "We identified significant downregulation of several metabolic pathways related to hepatic functionality, PPAR signaling, and drug metabolism for NFIB, NFIC, and NFIX, whereas pathways associated with cancer biology were significantly induced." (PMID 41106572, 2025). "In cancer research, it was found that the upregulation of NFIX causes poor prognosis due to its association with ROS." (PMID 41326361, 2025). "The work being reviewed highlights the role of NFIX in cancer, particularly by showing its strict association with increased oxidative stress." (PMID 36901722, 2023). "For example, RhoA/ROCK and JUNB signaling pathways or SOX4 overexpression, which control NFIX expression both during embryonic development and in the context of cancer, have been linked to oxidative stress." (PMID 36901722, 2023). "The role of NFIX in cancer proliferation, migration, and invasion has been linked to the expression of non-coding RNAs, namely miRNA and lncRNA." (PMID 36901722, 2023). "The role of NFIX in cancer proliferation, migration, and invasion has been linked to the expression of non-coding RNAs." (PMID 37686043, 2023). "circRNA NFIX had been implicated in the development of many other cancers in previous studies." (PMID 39135128, 2024). "One possible mechanism explaining the importance of NFIX in cancer might be dedifferentiation, which has recently been proposed as an emerging cancer hallmark." (PMID 36901722, 2023). "The significance of NFIX in the development of various cancers has been demonstrated by an increasing number of studies in recent years." (PMID 40000619, 2025). "Results revealed that circRNA NFIX silencing repressed the growth of cancer cells and induced cell apoptosis by upregulating miR‐214‐3p and inhibiting TRIAP1 expression, which was a potential biomarker for NSCLC." (PMID 39135128, 2024). "On the other hand, RNA-seq data showed that four other genes (DUSP6, NFIX, VIM, and SPARCL1) associated with cancer were also downregulated in CREB5 knockdown cells." (PMID 38418476, 2024). "These cellular processes are either well-documented hallmarks or emerging hallmarks of cancer, opening the possibility of an important role of NFIX in cancer." (PMID 36901722, 2023). "Thereafter, in the context of cancer, we will focus on how NFIX relates to oxidative stress and alters cell fate and how that impacts tumor progression." (PMID 36901722, 2023). "In this review, we examine different aspects of NFIX regulation, first in development and then in cancer, highlighting the important role of NFIX in oxidative stress and cell fate regulation in tumors." (PMID 36901722, 2023). "In this review, we build on the existing knowledge about the role of NFIX during development to examine its role in cancer." (PMID 36901722, 2023). "This study proposed that NFIX downregulation serves as a mechanism for cancer cells to reduce ROS production, thus, increasing their fitness." (PMID 36901722, 2023). "Collectively, this review increases our understanding of the involvement of NFIX in both development and cancer, which is essential for the establishment of targeted cancer therapies." (PMID 36901722, 2023). "In this scenario, it is possible that the control of NFIX expression leads to changes in the differentiation status and promotes a stem cell-like phenotype in cancer cells." (PMID 36901722, 2023). "In support of this notion, studies are recognizing NFIX and its target genes/proteins that are involved in oxidative stress as potential therapeutic targets for cancer therapy." (PMID 36901722, 2023). "Analysis of oxidative stress-related differentially expressed genes using data from 594 lung adenocarcinoma patients revealed that NFIX is downregulated in this type of cancer and has a direct correlation with poor prognosis." (PMID 36901722, 2023).